PCDHGB1 (protocadherin gamma subfamily B, 1)
Description:
Potential calcium-dependent cell-adhesion protein. May be involved in the establishment and maintenance of specific neuronal connections in the brain.
Synonyms: PCDH-gamma-B1
Tractability: Antibody: UniProt places it where antibodies can reach, with medium confidence; UniProt predicts a signal peptide or a membrane-spanning region; its Gene Ontology location is reachable by antibodies, with medium confidence; the Human Protein Atlas places it where antibodies can reach.
Gene: Protein-coding gene on chromosome 5 (141,350,099 to 141,512,975, forward strand). Ensembl gene ENSG00000254221.
Subcellular location: Cell membrane
Subcellular location (Human Protein Atlas): Plasma membrane; Vesicles; Focal adhesion sites; Midbody; Nucleoplasm
Gene Ontology:
Molecular function: cell adhesion molecule binding; calcium ion binding
Biological process: cell adhesion; homophilic cell-cell adhesion
Cellular component: plasma membrane; growth cone; membrane
Genetic constraint (gnomAD): Loss-of-function variants: 34 observed, 58.41 expected, observed/expected ratio (o/e) 0.58, 90% interval 0.44 to 0.77. The upper end of that interval is the gene's LOEUF score, 0.77, which puts it in group 3 of 6, group 1 being the genes least tolerant of losing a copy. Missense variants: 1,278 observed, 1,270.3 expected, observed/expected ratio (o/e) 1.01, 90% interval 0.96 to 1.05. Synonymous variants: 561 observed, 530.2 expected, observed/expected ratio (o/e) 1.06, 90% interval 0.99 to 1.13.
Homologues: Orthologues: mouse Pcdhgb1 (82% identical), rabbit PCDHGB1 (69% identical), pig PCDHGB1 (67% identical), dog PCDHGB1 (66% identical). Paralogues in human: PCDHGB2 (75% identical), PCDHGB5 (73% identical), PCDHGB4 (72% identical), PCDHGB6 (71% identical), PCDHGB3 (71% identical), PCDHGB7 (70% identical), PCDHGA5 (52% identical), PCDHGA6 (52% identical), PCDHGA11 (52% identical), PCDHGA7 (52% identical), PCDHGA10 (52% identical), PCDHGA12 (52% identical), and 49 more.
Diseases named in the same sentence as PCDHGB1 in open-access papers:
PCDHGB1 is named in the same sentence as 2 diseases in open-access papers, as found by Europe PMC text mining. Sharing a sentence is not in itself a finding about the gene and the disease. The quoted sentences say what the papers report.
cancer (2 papers, 2019 to 2024). A tumor composed of atypical neoplastic, often pleomorphic cells that invade other tissues. "The cell surface glycoproteins Protocadherins Gamma (Pcdhga1-9, Pcdhgb1-4) are linked to differentiation, cancer, aging, neurological disorders, and muscle weakness." (PMID 38594255, 2024). "In silico and data-mining analyses suggest that FAM171A1 has been predicted to interact with FAM171B, PCDHGB1, TNFRSF17, TMEM, CTDSPL, and NTRK1, many of which have been already implicated in various cancers suggesting most likely its possible role in the tumorigenesis." (PMID 30631046, 2019).
PCDHGB1 also shares sentences with these, for which no sentence is quoted: neurological disorders (1 paper).